RRS1 (regulator of ribosome synthesis 1)
Diseases named in the same sentence as RRS1 in open-access papers (continued):
Sharing a sentence is not in itself a finding about the gene and the disease.
breast tumor (2 papers, 2018 to 2023). "RRS1 showed significant changes in CNVs in breast tumours, compared with those for normal breast tissues (T/N = 1.705, P = 0.0002)." (PMID 30320499, 2018). "Standard immunohistochemical analyses demonstrated that RRS1 was predominantly expressed in the nucleolus of breast tumour epithelial cells, and 60.7% (147/242) of patients show overexpression of RRS1." (PMID 30320499, 2018).
retinoblastoma (2 papers, 2020 to 2023). A malignant tumor that originates in the nuclear layer of the retina. "Recent studies have identified an oncogenic role of RRS1 in some cancers, whereas the involvement of RRS1 in retinoblastoma (RB) remains to be determined." (PMID 33204686, 2020).
cervical clear cell carcinoma (1 paper, 2023). "Herein, we used comparative analysis to screen out genes with large differences in expression between HPV-negative and HPV-positive cervical clear cell carcinoma patients, including ALKBH7, MYCBP, MZF1, RNF207, RRS1, and TUSC2." (PMID 37654657, 2023).
dwarfism (1 paper, 2020). "Overexpression of RRS1 in an RPS4 overexpression line attenuates dwarfism and autoimmunity." (PMID 32050020, 2020).
lung carcinoma (1 paper, 2025). "Upregulated ribosome biogenesis regulator 1 homolog (RRS1) was negatively linked to the survival of patients with lung cancer, and its silencing could inhibit the malignant behavior of tumor cells and trigger apoptosis of cisplatin‐resistant A549 cells." (PMID 41031217, 2025).
prostate adenocarcinoma (1 paper, 2021). "It has been reported that higher levels of RSS1 and BOP1 are observed in 14% and 8%, respectively, of prostate adenocarcinomas and that higher levels of RRS1 mRNA correlate with shorter progression-free periods." (PMID 34572914, 2021). "We also analysed which genes encoding the proteins found in the HMGB1 interactomes are more frequently highly expressed in tumour samples from prostate adenocarcinomas, and we found among them RRS1 and BOP1, both important regulators of ribosome biogenesis." (PMID 34572914, 2021).
Stroke (1 paper, 2023). Sudden impairment of blood flow to a part of the brain due to occlusion or rupture of an artery to the brain. "The genes were found to be related to the immune dysregulation of stroke, and RRS1 was strongly associated with the prognosis, immune cell infiltration, microsatellite instability (MSI), and tumor mutation burden (TMB)." (PMID 37090698, 2023).
thyroid cancer (1 paper, 2018). "Further, the diagnostic value of RRS1 expression in thyroid carcinoma was evaluated by Receiver Operating Characteristic (ROC) curve analysis and Youden’s index." (PMID 29449788, 2018). "Notably, the present study confirmed the diagnostic value of RRS1 for thyroid carcinoma in both children and adults." (PMID 29449788, 2018). "Notably, the present study also confirmed the diagnostic value of RRS1 in thyroid carcinoma of both children and adults." (PMID 29449788, 2018). "Here we presumed that dysregulation of RRS1 in thyroid cancer played an important role in cell proliferation and thyroid carcinoma progression." (PMID 29449788, 2018). "The results showed that the expression of RRS1 in thyroid carcinoma tissues was higher than that in pericarcinous tissues, and it would be a potential indicator of thyroid carcinoma." (PMID 29449788, 2018). "These enrichments analysis supported the hypothesis that RRS1 is necessary to maintain identity of thyroid cancer cell." (PMID 29449788, 2018). "To investigate whether RRS1 differentially expressed in thyroid carcinoma, we detected the expression of RRS1 in total 38 thyroid samples (24 thyroid carcinoma; 14 pericarcinous tissues)." (PMID 29449788, 2018). "Our results support a novel function of RRS1 by promoting thyroid carcinoma cells proliferation, which could be a potential indicator of PTC in both children and adults." (PMID 29449788, 2018). "The results suggested that inhibitory proliferation and apoptosis of thyroid carcinoma cells could be induced by knock-down of RRS1." (PMID 29449788, 2018).
viral infection (1 paper, 2023). "Therefore, we hypothesized that RRS1 may be involved in viral infection." (PMID 38203476, 2023).
cancer (16 papers, 2017 to 2024). A tumor composed of atypical neoplastic, often pleomorphic cells that invade other tissues. "RRS1 functions as an oncogene in cancer, with RRS1 gene mutation and abnormal expression promoting tumor growth and metastasis." (PMID 38331968, 2024). "As the KEGG enrichment analysis results revealed that the intersection genes of NAFLD and IS were associated with cancer, the effect of RRS1 (the gene with the greatest prediction performance of NAFLD with IS) was further investigated in pan-cancer." (PMID 37090698, 2023). "Meanwhile, we pointed out that dysregulation of RRS1 may be a high risk factor for cancer in patients with NAFLD complicated by IS." (PMID 37090698, 2023). "Moreover, the findings of this research signified that RRS1 is a prognostic risk factor in various cancers." (PMID 37090698, 2023). "Transwell invasion assays along with scratch assays were carried out to evaluate RRS1’s influence on cancer cell invasion and migration." (PMID 38474562, 2024). "The data for normal tissue in the GTEx database were then collected, and RRS1 was found to be weakly expressed only in LAML but strongly expressed in 27 cancers, including ACC, BLCA, and BRCA." (PMID 37090698, 2023). "In DSS analysis, the expression of RRS1 was significantly associated with four cancers, namely, KIRP, PAAD, LUAD, and UCS, and was a risk factor in all four cancers." (PMID 37090698, 2023). "In the TCGA database, RRS1 was highly expressed in 18 cancer types, including CHOL, BRCA, and BLCA, with a statistical significance." (PMID 37090698, 2023). "Further research on RRS1 is expected to aid in the diagnosis and treatment of this type of cancer patient." (PMID 37090698, 2023). "Since ribosome biogenesis is a critical event during protein synthesis, researchers have paid attention to the pathological role of RRS1 in cancer development." (PMID 33204686, 2020). "As tumor cells often require a large amount of protein synthesis, the role of RRS1 in cancer development has been investigated." (PMID 33204686, 2020). "Similarly, Western blot results demonstrated a significant increase in RRS1 protein level in cancer tissues compared to BC-paired normal tissues." (PMID 38331968, 2024). "RRS1 may serve as a candidate gene for predicting the prognosis of patients with cancer who have NAFLD complicated by IS, which could aid in their diagnosis and treatment." (PMID 37090698, 2023). "RRS1 may be a candidate gene for predicting poor prognosis in patients with cancer who have NAFLD complicated by IS." (PMID 37090698, 2023). "RRS1 is a potential oncogene in various cancers, and therefore a promising therapeutic target." (PMID 33718361, 2021). "In addition, knockdown of RRS1 negatively regulates the cell cycle progression and induces apoptosis in cancer cells." (PMID 33204686, 2020). "Importantly, basal cancers express high mRNA levels of genes encoding regulators of ribosome biogenesis such as BYSL, RRS1, RIOK1, POLR1C, and POLR1E (group C)." (PMID 32054925, 2020). "Therefore, the immune-related gene RRS1 was selected for further pan-cancer analysis." (PMID 37090698, 2023). "Although the consequences of RRS1 overexpression on the regulation of ribosome biogenesis per se was not determined, other reports showing that high RRS1 is oncogenic in breast, thyroid, and liver cancers, clearly indicate that RRS1 represents a new promising target to be considered in CRC therapy." (PMID 33120992, 2020). "Overall, we found that ALKBH7, MYCBP, MZF1, RRS1, and TUSC2 were reported to be involved in the development and progression of cancer." (PMID 37654657, 2023). "The DFS study found a significant relationship among three cancers—OV, LIHC, and PAAD—and RRS1 expression." (PMID 37090698, 2023). "RRS1 silencing increased the sensitivity of MCF-7/DDP cells to cisplatin and inhibited cancer cell proliferation by blocking cell cycle distribution and enhancing apoptosis." (PMID 37049702, 2023).
cancer (continued). "Altogether, ALKBH7, MYCBP, MZF1, RRS1, and TUSC2 were reported to be involved in the development and progression of cancer, and dysregulation of these genes was known to be highly correlated with tumorigenesis." (PMID 37654657, 2023). "For IRS2, RRS1 and MRPL5, we observed that the fold change in expression is comparable in cancer and under BPA treatment, suggesting that BPA presence can bias the predictive power of these genes." (PMID 34062972, 2021). "We also found that RRS1 enhanced AKT/mTOR signaling activity, which is frequently activated in various cancers." (PMID 33204686, 2020). "RRS1 was related to B cells in 13 cancers, CD4+ T cells in 14 cancers, CD8+ T cells in 15 cancers, myeloid dendritic cells in 17 cancers, macrophages in 16 cancers, and neutrophils in 13 cancers according to TIMER analysis." (PMID 37090698, 2023). "The biological function of human RRS1 in cancer has not been revealed." (PMID 29449788, 2018).
tumor (15 papers, 2017 to 2025). "Overexpression of ATAD2 and PVT1 in 8q24.13, RAD54B, LAPTM4B, and RRS1 in 8q21.13 were reported to be associated with tumor proliferation and progression of HCC." (PMID 36010950, 2022). "In TCGA and GTEx databases, the differential expression analysis of RRS1 in 28 tumor types, including BRCA, LIHC, and STAD, showed statistical significance." (PMID 37090698, 2023). "The expression of RRS1 is significantly upregulated in a clinical CRC cohort, associated with tumor aggressiveness and poor overall survival." (PMID 33120992, 2020). "These tumours also showed reduced RRS1 protein and mRNA levels (P < 0.05), indicating that RRS1 shRNA expression persisted over the course of the experiment." (PMID 30320499, 2018). "Based on immunohistochemistry assay, we found that RRS1 expression was significantly higher in the tumor areas." (PMID 29137316, 2017). "Taken together, RRS1 is a useful biomarker in CRC patients that can be used to monitor the tumor progression after operation." (PMID 29137316, 2017). "Silencing of RRS1 suppressed cell proliferation and tumor formation of CRC cells, mainly through cell cycle arrest at the G2/M phase, enhanced apoptosis and angiogenesis inhibition." (PMID 29137316, 2017). "The TCGA database and analysis of four pairs of BC tumor tissues revealed an elevated RRS1 level." (PMID 38331968, 2024). "Additionally, IHC results demonstrated a decrease in RRS1-positive cells in tumor tissues following SNHG1 knockdown." (PMID 38331968, 2024). "Recent studies regarded RRS1 as a tumor promotor and concluded that overexpression of RRS1 could facilitate the growth and metastasis of various tumors." (PMID 36945018, 2023). "In addition, RRS1 regulates the balance between cytoplasmic membrane and endoplasmic reticulum, and its dysregulation in tumor cells can significantly alter their physiological functions." (PMID 33718361, 2021). "Furthermore, RRS1 knockdown suppressed the tumour formation and growth of MDA‐MB‐231 cells in nude mice." (PMID 30320499, 2018). "The copy numbers of RRS1 were higher in tumours compared with those for normal tissues." (PMID 30320499, 2018). "In addition, suppression of RRS1 blunted the tumor formation of CRC cells in nude mice." (PMID 29137316, 2017). "Knockdown of RRS1 in CRC cells RKO and HCT116 induced apoptosis and suppressed G2/M cell cycle transition, angiogenesis, cell proliferation and xenografted tumor formation." (PMID 29137316, 2017). "Tumor volume was evaluated from day 1 to day 27 and the results showed that tumorigenesis of CRC was dramatically blunted after RRS1 silencing." (PMID 29137316, 2017).
infection (8 papers, 2013 to 2024). The state of being infected such as from the introduction of a foreign agent such as serum, vaccine, antigenic substance or organism. "Due to the limitations of RRS1 antibodies in Co-IP experiments, we utilized lentiviral infection with Flag-tagged overexpressed RRS1 in BC cells and performed IP using anti-Flag antibodies." (PMID 38474562, 2024). "The interaction of AtWRKY52/RRS1 with R protein RPS4 protected the plants from infection by fungal and bacterial pathogens." (PMID 33176698, 2020). "BT-549 and MDA-MB-231 cells were infected with shRNA targeting RRS1 (sh-RRS1), control shRNA (sh-CON), scrambled control (OE-CON), and overexpressed RRS1 (OE-RRS1) through lentiviral infection technology, respectively." (PMID 38474562, 2024). "Residual EDS1-dependent resistance in rps4-21rrs1-1 to Pst/AvrRps4 infection is conferred by an RPS4- and RRS1-independent mechanism operating in Ws-0 and likely also in accession Col-0 expressing the respective RPS4Col and RRS1Col allelic variants." (PMID 24146667, 2013). "To further validate whether RRS1 activates the PI3K/AKT pathway through GRP78, we utilized lentiviral infection technology to overexpress RRS1 and employed siRNA to downregulate GRP78 expression." (PMID 38474562, 2024). "Numerous potential integrated decoys occur in RRS1 and RGA5 homologs and if they represent domains targeted by effector proteins, their identification and analysis should provide valuable information about cellular processes targeted by pathogens during infection." (PMID 25506347, 2014).
bacterial infection (1 paper, 2013). "Therefore, forced AvrRps4 localization to the nucleus or the cytoplasm does not alleviate the requirement for RPS4Ws or RRS1Ws in limiting bacterial infection or the extent of residual RPS4 and RRS1-independent resistance." (PMID 24146667, 2013).
RRS1 also shares sentences with these, for which no sentence is quoted: neuroblastoma (2 papers); ovarian carcinoma (2); gastric cancer (1); heart failure (1); hematoma (1); ischemic stroke (1); metastatic cancer (1); non-alcoholic fatty liver disease (1).